SLCO4C1 (solute carrier organic anion transporter family member 4C1)
Description:
Mediates the transport of organic anions such as steroids (estrone 3-sulfate, chenodeoxycholate, glycocholate) and thyroid hormones (3,3',5-triiodo-L-thyronine (T3), L-thyroxine (T4)), in the kidney. Capable of transporting cAMP and pharmacological substances such as digoxin, ouabain and methotrexate. Transport is independent of sodium, chloride ion, and ATP. Transport activity is stimulated by an acidic extracellular environment due to increased substrate affinity to the transporter. The driving force for this transport activity is currently not known (By similarity). The role of hydrogencarbonate (HCO3(-), bicarbonate) as the probable counteranion that exchanges for organic anions is still not well defined. Functions as an uptake transporter at the apical membrane, suggesting a role in renal reabsorption (By similarity). Involved in the renal secretion of the uremic toxin ADMA (N(omega),N(omega)-dimethyl-L-arginine or asymmetrical dimethylarginine), which is associated to cardiovascular events and mortality, and the structurally related amino acids L-arginine and L-homoarginine (a cardioprotective biomarker). Can act bidirectionally, suggesting a dual protective role of this transport protein; exporting L-homoarginine after being synthesized in proximal tubule cells, and mediating uptake of ADMA from the blood into proximal tubule cells where it is degraded by the enzyme dimethylarginine dimethylaminohydrolase 1 (DDAH1). May be involved in sperm maturation by enabling directed movement of organic anions and compounds within or between cells (By similarity). This ion-transporting process is important to maintain the strict epididymal homeostasis necessary for sperm maturation (By similarity). May have a role in secretory functions since seminal vesicle epithelial cells are assumed to secrete proteins involved in decapacitation by modifying surface proteins to facilitate the acquisition of the ability to fertilize the egg (By similarity).
Synonyms: OATP-M1; OATP4C1; OATPX; SLC21A20; OATP-H; PRO2176
Tractability: Small molecule: it belongs to a druggable protein family. Antibody: UniProt places it where antibodies can reach, with high confidence; its Gene Ontology location is reachable by antibodies, with high confidence; UniProt predicts a signal peptide or a membrane-spanning region; the Human Protein Atlas places it where antibodies can reach. PROTAC: ubiquitination databases record sites on it; a small molecule that binds it is known.
Target class: Electrochemical transporter; SLC superfamily of solute carriers; SLC21/SLCO family of organic anion transporting polypeptides; Transporter
Gene: Protein-coding gene on chromosome 5 (102,233,986 to 102,296,350, reverse strand). Ensembl gene ENSG00000173930.
Subcellular location: Basolateral cell membrane
Subcellular location (Human Protein Atlas): Plasma membrane; Cytosol; Nucleoplasm
Pathways (Reactome):
Immune System: Neutrophil degranulation
Transport of small molecules: Organic anion transport by SLCO transporters
Gene Ontology:
Molecular function: transmembrane transporter activity; secondary active transmembrane transporter activity
Biological process: sodium-independent organic anion transport; transmembrane transport
Cellular component: extracellular exosome; azurophil granule membrane; basolateral plasma membrane; plasma membrane; specific granule membrane; membrane
Genetic constraint (gnomAD): Loss-of-function variants: 45 observed, 57.05 expected, observed/expected ratio (o/e) 0.79, 90% interval 0.62 to 1.01. The upper end of that interval is the gene's LOEUF score, 1.01, which puts it in group 4 of 6, group 1 being the genes least tolerant of losing a copy. Missense variants: 779 observed, 765.57 expected, observed/expected ratio (o/e) 1.02, 90% interval 0.96 to 1.08. Synonymous variants: 263 observed, 282.95 expected, observed/expected ratio (o/e) 0.93, 90% interval 0.84 to 1.03.
Homologues: Orthologues: chimpanzee SLCO4C1 (99% identical), macaque SLCO4C1 (94% identical), mouse Slco4c1 (81% identical), rat Slco4c1 (81% identical), rabbit SLCO4C1 (81% identical), dog SLCO4C1 (76% identical), pig SLCO4C1 (74% identical), guinea pig SLCO4C1 (67% identical), tropical clawed frog slco4c1 (52% identical), Caenorhabditis elegans F53B1.8 (30% identical), Caenorhabditis elegans Y70G10A.3 (26% identical), Caenorhabditis elegans K02G10.5 (24% identical). Paralogues in human: SLCO4A1 (39% identical), SLCO6A1 (37% identical), SLCO5A1 (32% identical), SLCO3A1 (29% identical), SLCO1B1 (26% identical), SLCO1C1 (26% identical), SLCO1B3 (26% identical), SLCO2A1 (26% identical), SLCO2B1 (25% identical), SLCO1A2 (23% identical).
Diseases named in the same sentence as SLCO4C1 in open-access papers:
SLCO4C1 is named in the same sentence as 24 diseases in open-access papers, as found by Europe PMC text mining. Sharing a sentence is not in itself a finding about the gene and the disease. The quoted sentences say what the papers report.
renal failure (9 papers, 2011 to 2025). "Overexpression of the human kidney-specific organic anion transporter SLCO4C1 in rat kidneys reduces hypertension, cardiac hypertrophy, and inflammation in renal failure." (PMID 31998783, 2020). "Because the expression of SLCO4C1 was decreased in the renal failure, these data suggest that the down-regulation of SLCO4C1 is one of the causes of the accumulation of uremic toxins in CKD." (PMID 23874392, 2013). "It has been reported that the expression levels of various transporters change in the renal failure, and the expression level of SLCO4C1 expression is also down-regulated in the renal failure." (PMID 23874392, 2013). "In addition, using a rat model of renal failure, the basolaterally expressed kidney-specific organic anion transporting polypeptide 4C1 (SLCO4C1) was recently shown to facilitate the removal of several uremic toxins, including guanidino succinate, in the proximal tubule." (PMID 21483698, 2011). "However, the down-regulation mechanism of SLCO4C1 in the renal failure has not been well elucidated." (PMID 23874392, 2013).
endometrial cancer (5 papers, 2020 to 2024). Primary or metastatic malignant neoplasm involving the endometrium (mucous membrane that lines the endometrial cavity). "Interference with SLCO4C1 expression caused inactivation of PI3K/Akt pathway causing apoptosis in endometrial cancer." (PMID 38226966, 2024). "Altered OATP4C1 expression has been linked to CVD events and endometrial cancer tissues, and genetic variants of the SLCO4C1 gene were also found to be associated with obesity." (PMID 33302555, 2020). "Researchers have found that SLCO4C1 regulates the proliferation, apoptosis, migration, and other characteristics of endometrial cancer cells by regulating the PI3K/AKT signaling pathway." (PMID 34823498, 2021). "The overexpression of the SLCO4C1 gene has recently been described in endometrial cancer tissue, and it was shown that the downregulation of this gene can promote apoptosis in endometrial cancer cell lines." (PMID 33498201, 2021). "The Cancer Genome Atlas data showed that upregulation of SLCO4C1 is closely related to the clinical stage and survival time of endometrial cancer." (PMID 34823498, 2021). "Similarly, SLCO4C1 acting as an oncogene in endometrial cancer but as cancer suppression in head and neck cancer." (PMID 38226966, 2024). "However, the low expression of SLCO4C1 inhibited the biological behavior of endometrial cancer cells and could promote the apoptosis of their tumor cells." (PMID 38226966, 2024). "Studies have shown that SLCO4C1 promotes the metastasis and invasion of endometrial cancer, influences the epithelial-mesenchymal transition (EMT) phenotype of endometrial cancer cells, and regulates the expression of EMT-related proteins." (PMID 37664112, 2023).
Hypertension (5 papers, 2018 to 2025). The presence of chronic increased pressure in the systemic arterial system. "SLCO4C1 is an organic anion that transports polypeptides whose transporter eliminates uremic toxins and attenuates hypertension and renal inflammation." (PMID 36104709, 2022). "As an in vivo proof-of-concept, in transgenic rats, SLCO4C1 (SLC21A20) overexpression decreased kidney inflammation and hypertension following subtotal nephrectomy." (PMID 30029499, 2018).
head and neck cancer (4 papers, 2020 to 2024). A primary or metastatic malignant neoplasm affecting the head and neck. "SLCO4C1 is a key tumor suppressor gene in head and neck cancer that can be inactivated by “larger promoter” methylation and somatic mutations." (PMID 31998783, 2020). "SLCO4C1 in head and neck cancer was a tumor suppressor gene." (PMID 38226966, 2024).
Obesity (4 papers, 2017 to 2025). Accumulation of substantial excess body fat. "The other two variants, NLRP13 and SLCO4C1, are found to be implicated in different types of cancer, diabetes type 2, eye movement dysfunction and obesity." (PMID 32973469, 2020). "A total of 10 shared co-expressed partners were identified in the analysis between our 4 novel strongest candidate genes (GRIK1, GRM7, GRPR and SLCO4C1) and the set of 15 obesity-related genes described in the literature." (PMID 28489853, 2017). "To further assess the possible implication of these strong candidate genes (GRIK1, GRM7, GRPR and SLCO4C1), we determined the co-expression patterns between them and 15 well-defined genes from the leptin-melanocortin pathway previously related to obesity." (PMID 28489853, 2017). "Among those, the genes encoding the neuropeptide Y (NPY), two glutamate receptors (GRIK1, GRM7), the X-linked gastrin-peptide receptor (GRPR), and the organic anion transporter (SLCO4C1) are novel obesity candidate genes that may contribute to highly penetrant forms of familial obesity." (PMID 28489853, 2017). "Interestingly, we found additional RSVs in patients in 4 of the selected genes (NPY, GRPR, SLCO4C1 and GRIK1) reinforcing their putative role in the pathophysiology of obesity." (PMID 28489853, 2017).
prostate carcinoma (4 papers, 2020 to 2023). A carcinoma that arises from epithelial cells of the prostate gland. "In previous research, SLCO4C1 promoter methylation have been identified as prognostic biomarker for prostate cancer." (PMID 33203797, 2020). "Moreover, mRNA expression levels of SLCO1B1, SLCO1B3, SLCO2B1 and SLCO4C1 were found to be higher in castration-resistant prostate cancer metastases as compared to in untreated prostate cancer." (PMID 36839686, 2023).
chronic kidney disease (3 papers, 2012 to 2025). Impairment of the renal function secondary to chronic kidney damage persisting for three or more months. "In addition to its function in chronic kidney disease, SLCO4C1 has also been found to be involved in the occurrence of various tumors." (PMID 34823498, 2021).
diabetes (1 paper, 2019). "Here we show using untargeted metabolomics that levels of phenyl sulfate, a gut microbiota-derived metabolite, increase with the progression of diabetes in rats overexpressing human uremic toxin transporter SLCO4C1 in the kidney, and are decreased in rats with limited proteinuria." (PMID 31015435, 2019).
schizophrenia (1 paper, 2018). A major psychotic disorder characterized by abnormalities in the perception or expression of reality. "In addition to CSPG4P11, which showed a significant SMR association with schizophrenia in the present study, these included CD46, encoding the CD46 complement regulatory protein, GOLGA2P7, encoding GOLGA2 pseudogene 2, and SLCO4C1, encoding Solute Carrier Organic Anion Transporter Family Member 4C1." (PMID 30419947, 2018).
cancer (8 papers, 2019 to 2024). A tumor composed of atypical neoplastic, often pleomorphic cells that invade other tissues. "Six additional genes (SLC10A6, SLC22A1, SLC51A, SLC51B, SLCO1C1, SLCO4C1) were included to finally examine the expression of 15 genes encoding E1-S transporters in the total of 36 pairs of cancer and adjacent control tissue." (PMID 33917029, 2021). "Although other members of the OATP family are expressed in some types of tumors and can transport antitumor drugs, such as OATP1C1 (SLCO1C1), which transports docetaxel, OATP4C1 (SLCO4C1), methotrexate, and OATP5A1 (SLCO5A1), satraplatin, their role in cancer chemoresistance is poorly understood." (PMID 39143954, 2024).
tumor (5 papers, 2017 to 2024). "The study showed that advanced tumour stages (pT) were associated with higher methylation levels at SLCO4C1 CpG sites (cg06480736, cg19774478, cg19788741 and cg22149516)." (PMID 31288850, 2019). "SLCO4C1 has been implicated in tumor progression, there may be heterogeneity in the role in each tumor." (PMID 38226966, 2024). "However, a few studies have reported SLCO4C1 as a potential tumour suppressor gene and shown that low expression of SLCO4C1 may be associated with the development of tumours." (PMID 31288850, 2019). "Total RNA extraction and qRT-PCR were used to reveal the difference in SLCO4C1 expression between tumour and normal tissues." (PMID 31288850, 2019). "SLCO4C1 in tumour tissues showed significantly higher levels of promoter methylation than that in normal tissues." (PMID 31288850, 2019). "Bisulfite amplicon sequencing (BSAS) further confirmed a higher methylation level at the SLCO4C1 promoter in tumour tissues." (PMID 31288850, 2019). "Among the CpG sites, four sites (cg06480736, cg19774478, cg19788741 and cg22149516) located in the promotor region (TSS200-1500) of SLCO4C1 were found to be significantly hypermethylated in tumour tissues." (PMID 31288850, 2019). "The results showed that SLCO4C1 harbours a relatively higher level of methylation in tumour tissues from a validation cohort (TCGA)." (PMID 31288850, 2019). "In the analysis of clinicopathological parameters, the results showed that methylation levels at all four sites on the SLCO4C1 gene were related to advanced tumour stages." (PMID 31288850, 2019). "The tumor-suppressive role of SLCO4C1 in HCC has been confirmed." (PMID 38226966, 2024). "In this study, we provided the first evidence of SLCO4C1 functioning as a tumor suppressor in HCC." (PMID 38226966, 2024). "Moreover, we successfully identified and validated the tumor-suppressive role of SLCO4C1 in HCC, which holds great potential for improving the diagnosis and treatment of HCC patients." (PMID 38226966, 2024). "Our study elucidates the heterogeneity of SLCO4C1 in HCC tumor progression." (PMID 38226966, 2024). "The difference in SLCO4C1 expression between tumour and normal tissues was quantified by qRT-PCR." (PMID 31288850, 2019). "Finally, these four CpG sites of SLCO4C1 were validated, showing significantly different methylation levels between adjacent tissues and tumour tissues in TCGA cohort." (PMID 31288850, 2019). "Furthermore, BSAS confirmed a high level of methylation at the SLCO4C1 promoter in tumour tissues and a relatively low level of methylation in BPH tissues." (PMID 31288850, 2019). "Therefore, the previous analysis confirmed the presence of a high level of methylation at the SLCO4C1 promoter in tumour tissues and a relatively low level of methylation in normal tissues." (PMID 31288850, 2019). "The results of qRT-PCR validated that tumour tissues had a relatively lower expression of SLCO4C1." (PMID 31288850, 2019). "There was only one UB anchor gene (SLCO4C1) in the GUDMAP database, which was differentially expressed in the triphasic tumours relative to the blastemal tumours." (PMID 29040332, 2017). "The results revealed that expression levels of SLCO4C1, POU4F1, DNASE1L2, WDR72, LPO, and C7 in tumor tissues were significantly higher than those in normal tissues, while the expression differences of SLC4A4, CELF4, and SLC11A1 were not statistically significant." (PMID 37745305, 2023).
infection (1 paper, 2016). The state of being infected such as from the introduction of a foreign agent such as serum, vaccine, antigenic substance or organism. "However, the expression of Pkd2, Pkhd1, Kif12, Cadherin16 and Socs3, which are known as HNF-1β target genes, did not change (data not shown), and only a few genes, including NR1H4, MITF, SLC3A1, and SLCO4C1, were significantly upregulated 9 h after Ad-HNF1B infection." (PMID 27196561, 2016).
SLCO4C1 also shares sentences with these, for which no sentence is quoted: Amyloid (1 paper); cardiac hypertrophy (1); childhood asthma (1); colorectal cancer (1); diabetes type 2 (1); dyslipidemia (1); fibrosis (1); head and neck squamous cell carcinoma (1); hepatocellular carcinoma (1); Infertility (1); kidney damage (1); liver failure (1).